TLR4 (toll like receptor 4)
Diseases named in the same sentence as TLR4 in open-access papers (continued):
Sharing a sentence is not in itself a finding about the gene and the disease.
silicosis (6 papers, 2021 to 2025). Silicosis is a respiratory disease caused by breathing in (inhaling) silica dust. "Silicosis causes lung-specific flora dysbiosis → BALF LPS ↑ → activates TLR4-NF-κB, driving inflammation–fibrosis; broad-spectrum antibiotics partially reverse this." (PMID 41395479, 2025). "Collectively, our work lends strong evidence to support the benefits of thalidomide in limiting ER stress, the inflammatory response, and the TLR4-NF-κB pathway activation accompanying silicosis and provides valuable insights into the mechanisms underlying the attenuation of this disease." (PMID 35628464, 2022). "We verified this possibility by detecting mRNA and protein levels of several essential gene factors in the TLR4-MyD88 pathway and found that these markers in silicosis mice declined under Tet treatment." (PMID 34417574, 2022). "For example, how can we explain the dual effect of TLR4 targeting macrophage autophagy in the silicosis progression?" (PMID 33466366, 2021). "Are treatments targeting autophagy activity regulated by TLR4 expected to be an effective therapy for intervention in silicosis?" (PMID 33466366, 2021). "Should the function of the p62-Keap1-Nrf2 axis and the interaction between p62 and TLR4 in the macrophage autophagy of silicosis be further explored?" (PMID 33466366, 2021). "In addition, we report that thalidomide mediated the alleviation of silicosis via the inhibition of ER stress, the inflammatory response, and the TLR4-NF-κB." (PMID 35628464, 2022). "How does the TLR4 activity changes with the development of silicosis?" (PMID 33466366, 2021). "LPS further intensifies the blockade of AM autophagic degradation of silicosis patients via the activation of toll-like receptor 4 (TLR4)/myeloid differentiation factor 88 (MyD88) and the toll-like receptor adaptor molecule 1 (TLRAM1) signaling pathway or inhibition of mTOR signaling pathway." (PMID 34360876, 2021). "Furthermore, our work also provides strong evidence for clinical strategies that combine thalidomide with other inhibitors of ER stress, the inflammatory response, and the TLR4-NF-κB pathway to increase the efficacy and therapeutic range available for silicosis patients." (PMID 35628464, 2022). "However, with the development of human silicosis, the expression of TLR4 is reduced in AMs." (PMID 33466366, 2021). "Results reflected those from the Western blot and tissue immunofluorescence staining; TLR4 and TNF-α were strongly expressed in the silicosis model group, and with the treatment of thalidomide, the expression levels of TLR4 and TNF-α were decreased." (PMID 35628464, 2022). "Notably, the expression of myeloid differentiation factor 88 (MyD88) and toll-like receptor adaptor molecule 1 (TLRAM1) elevate in AMs of humans treated with LPS, indicating that LPS-regulated autophagy may be dependent on TLR4-MyD88 or TLR4-TLRAM1 signaling pathway in human silicosis." (PMID 33466366, 2021). "Interestingly, the integration of TLR-4/NLRP3/TGF-β signaling and metabolomics verified the importance of macrophage polarization in the silicosis fibrosis process." (PMID 34336106, 2021). "Furthermore, TLR4 inhibitor TAK-242 suppresses the release of Interleukin-1β (IL-1β) and IL-6 in the U937-differentiated macrophages exposed to silica, suggesting the activation of TLR4 may intensify silica-induced silicosis fibrosis." (PMID 33466366, 2021).
spinal cord ischemia (6 papers, 2015 to 2023). Reduced blood flow to the spinal cord which is supplied by the anterior spinal artery and the paired posterior spinal arteries. "The aim of this study is to investigate the roles of exogenous activation of CB2R on attenuating neurological deficit and blood-spinal cord barrier (BSCB) disruption during rat spinal cord ischemia reperfusion (I/R) injury, through modulation of the TLR4/MMP9 axis." (PMID 32248810, 2020). "In addition, some studies have reported that DEX preconditioning effectively reduces the inflammatory response of myocardial, renal and spinal cord ischemia by downregulation of high-mobility group protein B1 (HMGB1)/toll-like receptor 4 (TLR4) pathways." (PMID 28729825, 2017). "For example, TLR4 mediates NF-κB/IL-1β activation which can aggravate the inflammatory injury of the blood spinal cord barrier (BSCB) and nerve cells after spinal cord ischemia reperfusion." (PMID 36714328, 2023). "This study investigated the effects of dexmedetomidine on the toll-like receptor 4 (TLR4)-mediated nuclear factor κB (NF-κB) inflammatory system and caspase-3 dependent apoptosis induced by spinal cord ischemia–reperfusion injury." (PMID 30031397, 2018).
thymoma (6 papers, 2014 to 2024). A neoplasm arising from the epithelial cells of the thymus. "The loss of antigen presentation capacity in TLR4‐deficient dendritic cells can be restored by CQ, possibly by raising lysosomal pH, which contributed to tumour size reduction in a tlr4−/− thymoma mouse model." (PMID 32715647, 2020). "TLR4 mRNA levels were found to be higher in thymic tissue of non-thymomatous MG patients and thymic tissue adjacent to thymomas compared to thymuses from cardiac surgery patients without MG." (PMID 24705787, 2014).
ulcer (6 papers, 2013 to 2023). "We also analyzed the association of the TLR4 polymorphisms and the histological findings of the dyspepsia and ulcer patients’ gastric and duodenal biopsies." (PMID 26161647, 2015). "HMGB1 and Nuclear factor kappa (NF-B) expression, IL-1β and Nrf2 contents showed an increase along with ulcer development, concurrent with an increase in immunohistochemical TLR-4 level." (PMID 37371993, 2023). "TLR4 and RAGE deficiency enhanced ulcer healing and reduced the level of TNFα, whereas ulcer healing in TLR2 knockout (KO) mice was similar to that in wild-type mice." (PMID 24244627, 2013). "So in cases where H. pylori is able to avoid or locally neutralize the low pH, the constant activation of wild type TLR4 +896/+1196 receptors could be hypothesized to lead to hypergastrinemia and increased acid load leading to an ulcer." (PMID 26161647, 2015). "Thus, TLR4 and RAGE play critical roles in pathogenesis mediated by the HMGB1-associated pathway, including the pathway in our ulcer healing model." (PMID 24244627, 2013). "However, in combination with the role that TLR4 could induce basic protective immunoreaction, TLR4 plays dual roles in protection and injury; thus, it might be a drug-targeting site to prevent dysbiosis-induced ulcer deterioration." (PMID 36846768, 2023). "Since the ulcer risk genotype of TLR4 associated with high serum gastrin but not with gastric inflammation, we suggest that the role of TLR4 in the regulation of gastric secretion is more important in mediating the ulcer risk than its direct proinflammatory effects." (PMID 26161647, 2015). "We also investigated which receptor among TLR2, TLR4, or RAGE mediates HMGB1’s effects on ulcer healing." (PMID 24244627, 2013). "Our study further demonstrates that F.AOH could be employed as an anti-GU plant component as it has involved in TLR4/NF-κB and TRPV1 signalling pathways and gastric mucosal ulcer healing." (PMID 36541204, 2023). "Thus TLR4 activation and its effects on gastrin and acid secretion might also have a role in the pathogenesis of NSAID ulcers." (PMID 26161647, 2015). "The expression of TLR4 mRNA was not affected by the induction of ulcer." (PMID 24244627, 2013). "Additionally, TLR4 and RAGE deficiency promotes ulcer healing, and exogenous HMGB1 fails to delay ulcer healing in TLR4 KO and RAGE KO mice." (PMID 24244627, 2013). "In TLR4 KO and RAGE KO mice, exogenous HMGB1 did not affect ulcer healing and TNFα expression." (PMID 24244627, 2013).
Yersinia infection (6 papers, 2021 to 2025). "The apoptotic response to Y. pseudotuberculosis was considerably reduced in BMDMs from TLR4-deficient mice, suggesting that PKR is required for TLR4-dependent apoptosis during Yersinia infection." (PMID 34305942, 2021). "It has also been shown that TLR4 plays an important role in the induction of apoptosis in macrophages following Yersinia infection." (PMID 40184418, 2025). "In contrast, caspase-8 promotes TLR4-induced NF-κB activation in mouse B cells independent of its protease enzymatic activity, whereas the production of inflammatory cytokines (TNF, IL-6, IL-12) upon Yersinia infection relies on the protease enzymatic activity of caspase-8." (PMID 38789425, 2024).
acute monocytic leukemia (5 papers, 2018 to 2025). Acute monoblastic leukemia (AML-M5), is one of the most common subtypes of acute myeloid leukemia (AML) that is either comprised of more than 80% of monoblasts (AML-M5a) or 30-80% monoblasts with (pro)monocytic differentiation (AML-M5b). "HM exerts distinct anti-proliferative effects on human acute monocytic leukemia and embryonic kidney cells mainly through cell cycle interference in a TLR4-independent manner and through apoptosis induction in a TLR4-dependent manner, as observed in only the THP-1 cells." (PMID 32448225, 2020). "In lipopolysaccharide (LPS)-induced inflammation in the human acute monocytic leukemia cell line THP-1, KO–water emulsion treatment inhibited TNF-α release by inactivating macrophage binding to toll-like receptor-4 (TLR4), which plays a significant role in the innate immune response." (PMID 40806489, 2025). "To date, no cytotoxic studies have been reported of HM in TLR4-positive acute monocytic leukemia THP-1 cells compared to TLR4-negative human embryonic kidney HEK293 cells." (PMID 32448225, 2020).
alcoholic cirrhosis (5 papers, 2013 to 2024). "In addition, Toll-like receptor 4 (TLR4) identifies lipopolysaccharides (LPS) (products of gram-negative bacteria) that are usually elevated in persons with excessive alcohol intake and alcoholic cirrhosis." (PMID 35008267, 2021). "In contrast to sera from healthy controls, sera from patients with alcoholic cirrhosis induced CXCL1 secretion in TLR2- (p=0.016) and TLR4- (p=0.008) transfected HEK293 cells." (PMID 24260493, 2013).
alveolitis (5 papers, 2008 to 2020). "Challenge-induced alveolitis was weaker in wP- and aP-vaccinated Tlr4-deficient mice and in aP-vaccinated wild-type animals, compared to their adjuvant controls." (PMID 18498620, 2008). "Finally, we reported the lung phenotype of toll-like receptor-4 (Tlr4)-deficient and Tlr2-deficient mice to not differ from that of wild type mice in terms of survival time post-irradiation, or by histological evidence of alveolitis or fibrosis." (PMID 22891164, 2012). "Moreover, in a naïve cotton rat model, both PreF and PostF immunization elicited protective RSV immunity without inducing alveolitis when paired with the Th1-skewing toll-like receptor 4 agonist (TLR4), glucopyranosyl lipid A (GLA)." (PMID 32849580, 2020).
amyloidosis (5 papers, 2016 to 2023). A disorder characterized by the localized or diffuse accumulation of amyloid protein in various anatomic sites. "In AD mouse models, activation of TLR4 can enhance the clearance of amyloid plaques through phagocytosis of glial cells, thereby decreasing amyloid plaque load." (PMID 36046763, 2022). "The presence of amyloid is detrimental in activating the TLR4-mediated NF-κB/MAPK inflammatory axis, promoting the discharge of pro-inflammatory and neurotoxic cytokines (IL-1 β, IL-6, and TNF-α)." (PMID 32046119, 2020). "In support of this concept is the demonstration that genetic deletion of TLR4, required for efficient microglial detection of Aβ, is sufficient in dampening early-stage neuro-inflammatory responses leading to enhanced amyloidosis and impaired cognitive function in APPSWE/PS1ΔE9 mice." (PMID 27443609, 2016). "SAA receptors, such as SELS (glucose homeostasis and ER stress), ABCA1, ABCA7, SCARB1 (cholesterol efflux), CD36, TLR2, TLR4, CST3 (inflammatory signaling), FPR2 (chemotaxis and immune cell activation), and AGER (amyloidosis), have been reported previously." (PMID 27799725, 2016). "Likewise, TLR4 levels and IL-1β gene expression were significantly increased in hippocampal differentiated mice models without amyloidosis (i.e., entorhinal cortex damaged mice) compared with pseudodamaged mice." (PMID 36046763, 2022). "Similarly, in a mouse model of hippocampal differentiation (at 7 days post-lesion) without amyloidosis (i.e., the entorhinal cortex lesioned mouse), hippocampal TLR4 and IL-1β mRNA expression levels were significantly elevated compared to sham-lesioned mice." (PMID 32046119, 2020).
antiphospholipid syndrome (5 papers, 2015 to 2019). A disorder caused by the presence of autoantibodies directed against phospholipids, causing a hypercoaguable state, which may result in blood clots, stroke, heart attack, and in women, significant pregnancy-related complications, including miscarriage and still birth. "Elevated TLR4 messenger RNA expression of blood vessels was found in antiphospholipid syndrome (APS) associated with increased rates of cardiovascular morbidity and mortality, suggesting a role of TLR4 in angiogenesis regulation." (PMID 29029545, 2017). "Annexin A2 activates TLR-4 to regulate smooth muscle cell proliferation and macrophage cytokine production and is an “adaptor” for TLR-4 in a multiprotein signalling scaffold on endothelial cells in antiphospholipid syndrome." (PMID 25878399, 2015).
apical periodontitis (5 papers, 2017 to 2026). "A recent study on apical periodontitis found that FSH aggravated inflammation by enhancing the expression of IL-1 β, IL-6, TNF and Toll-like receptor 4 in human periodontal ligament cells." (PMID 35527996, 2022).
Arrhythmia (5 papers, 2020 to 2025). Any cardiac rhythm other than the normal sinus rhythm. "Second, the temporal profile of TLR4 activation in the PVN (peaking at 3–7 days post-MI) correlates with the window of highest arrhythmia risk." (PMID 41614801, 2025). "It is clear that the inhibition of TLR4 within the PVN significantly reduced the incidence of VAs after MI according to the significant differences in the arrhythmia scores." (PMID 35393774, 2022). "These mechanistic links demonstrate that TLR4-mediated neuroinflammation is not merely associated with arrhythmias but represents a direct causal pathway from central immune activation to peripheral arrhythmogenic remodeling." (PMID 41614801, 2025). "The signaling pathway of Toll-like Receptor 4 (TLR4) plays a central role in Dox-induced cardiac inflammation, which may be consistent with the mechanism of arrhythmia induced by ibrutinib." (PMID 38572424, 2024). "In conclusion, the present study provided novel insights that SSYX may exert anti-arrhythmia effect via increased Ito, ICa-L, and Cx43 expression through regulating TLR4/MyD88/CaMKII signaling pathway, which may be the mechanism of electrical remodeling MetS-induced VA." (PMID 32733242, 2020). "The levels of TLR4 and MyD88 and the nuclear translocation of NF‐kB within the PVN were increased after MI, while sympathetic activation and arrhythmia scores were increased and cardiac function was decreased." (PMID 35393774, 2022).
autoimmune uveitis (5 papers, 2013 to 2024). An autoimmune form of uveitis (disease). "The gene product of fat mass and obesity‐associated (FTO) mitigated the severity of autoimmune uveitis by modulating microglial phenotypes through the GPC4/TLR4/NF‐κB signaling pathway." (PMID 39611043, 2024). "The suppression of Galectin‐3 reduced microglial reactivity and inflammatory reactions via the TLR4/MyD88/NF‐κB signaling cascade in autoimmune uveitis." (PMID 39611043, 2024). "In other experiments, it has been shown that Gal-3 promotes inflammation through the TLR4 (toll-like receptor 4)/MyD88 (myeloid differentiation primary response 88)/NF-κB (nuclear factor kappa B) pathway in microglia and in animal models of experimental autoimmune uveitis." (PMID 39125698, 2024). "Our previous studies showed that signaling of TLR2, TLR3, TLR4, and TLR9 is highly redundant in the adjuvant effect needed to induce experimental autoimmune uveitis (EAU)." (PMID 23207548, 2013).
bacterial vaginosis (5 papers, 2011 to 2024). Infection caused by bacterial overgrowth in the vagina. "TLR4 polymorphisms are also linked to premature delivery, which is a documented side effect of bacterial vaginosis (BV)." (PMID 39165943, 2024). "Accordingly, lavage from women with bacterial vaginosis, an imbalance of naturally occurring bacterial flora, showed increased TNF-α secretion and TLR4 mRNA expression, illustrating the capacity of these flora to trigger immune responses." (PMID 21253014, 2011). "Bacterial vaginosis was characterized by reduced IL-18 and GATA3 mRNA expression; anaerobic vaginitis was accompanied by increased IL-1b, IL-10, and TLR4 mRNA levels; increased IL-1b and TLR4 mRNAs were detected in vulvovaginal candidiasis." (PMID 38203620, 2023).
Bovine mastitis (5 papers, 2018 to 2025). INFLAMMATION of the UDDER in cows. "Studies have shown that LPS-induced inflammatory response in the mammary gland by binding to the toll-like receptor 4 of the mammary epithelial cell membrane, which is similar to the inflammatory response of bovine mastitis." (PMID 29904013, 2018). "miR-146 has also been studied in bovine mastitis, and it has been shown to play a negative feedback role in the inflammatory process by down-regulating the Toll-Like Receptor 4/TNF Receptor-Associated Factor 6/NF-κB (TLR4/TRAF6/NF-κB) pathway." (PMID 40001538, 2025). "Our data suggest that genes TLR4, NOD2, CXCL8, and OAS2 are key components involved in the host immune response to bovine mastitis and that the lncRNAs MSTRG25101.2, MSTRG.56327.1, and MSTRG.18968.1 adjacent to the SCC QTL and SCS QTL may potentially regulate expression of these candidate genes." (PMID 36204322, 2022).
cerebral aneurysms (5 papers, 2017 to 2023). "The expression of TLR4 was present in the endothelial cells and adventitia in human unruptured cerebral aneurysms, whereas rats presented it only in endothelial cells." (PMID 38137108, 2023). "It has been shown that the pathway involving TLR4 and MyD88 promotes tissue remodeling and rupture of a brain aneurysm." (PMID 35655323, 2022). "In particular, enhancement of the expression of TLR4 on the endothelial cell layer of human cerebral aneurysms has proposed the possible role of TLR4 in the formation of brain aneurysms." (PMID 34200356, 2021). "Toll-like receptor signaling, particularly the activation of TLR4 (Toll-like receptor 4), drives macrophages to a preferential M1 phenotype in cerebral aneurysms." (PMID 29445758, 2017). "Enhancement of TLR4 expression on the endothelial cell layer in the wall of the human cerebral aneurysm has been suggested that TLR4 may play an important role in the formation of brain aneurysm." (PMID 32264928, 2020).
chronic rhinosinusitis (5 papers, 2005 to 2025). Chronic form of sinusitis. "Our data appear in line with previous findings of Dong and coworkers who observed an increased TLR4 expression in chronic rhinosinusitis epithelial cells of inferior turbinate nasal mucosa, as compared to healthy adult volunteers." (PMID 22577387, 2012). "TLR4 was over expressed in the epithelium of chronic rhino-sinusitis." (PMID 22577387, 2012). "In chronic rhinosinusitis we found that TLR4 is significantly overexpressed." (PMID 22577387, 2012).